PYGO2 (pygopus family PHD finger 2)
Description:
Involved in signal transduction through the Wnt pathway.
Synonyms: 1190004M21Rik
Tractability: Small molecule: a structure with a bound ligand is known. PROTAC: ubiquitination databases record sites on it.
Gene: Protein-coding gene on chromosome 1 (154,957,026 to 154,963,853, reverse strand). Ensembl gene ENSG00000163348.
Subcellular location: Nucleus
Subcellular location (Human Protein Atlas): Nucleoplasm; Plasma membrane
Pathways (Reactome):
Signal Transduction: Deactivation of the beta-catenin transactivating complex; Formation of the beta-catenin:TCF transactivating complex
Gene Ontology:
Molecular function: protein binding
Cellular component: beta-catenin-TCF complex; nucleoplasm; nucleus
Genetic constraint (gnomAD): Loss-of-function variants: 7 observed, 19.62 expected, observed/expected ratio (o/e) 0.36, 90% interval 0.2 to 0.67. The synonymous counts are far from expectation, so gnomAD's model fits this gene poorly and the ratio says little. Missense variants: 494 observed, 452.03 expected, observed/expected ratio (o/e) 1.09, 90% interval 1.01 to 1.18. Synonymous variants: 218 observed, 174.76 expected, observed/expected ratio (o/e) 1.25, 90% interval 1.12 to 1.4.
Homologues: Orthologues: chimpanzee PYGO2 (99% identical), macaque PYGO2 (99% identical), rabbit PYGO2 (97% identical), dog PYGO2 (97% identical), mouse Pygo2 (97% identical), rat Pygo2 (96% identical), guinea pig PYGO2 (96% identical), zebrafish pygo2 (51% identical), Drosophila melanogaster pygo (35% identical), Caenorhabditis elegans pygo-1 (22% identical). Paralogues in human: PYGO1 (35% identical).
Diseases named in the same sentence as PYGO2 in open-access papers:
PYGO2 is named in the same sentence as 44 diseases in open-access papers, as found by Europe PMC text mining. Sharing a sentence is not in itself a finding about the gene and the disease. The quoted sentences say what the papers report.
breast carcinoma (19 papers, 2015 to 2025). "Additionally, the expression of miR-516a-3p was negatively associated with poor prognosis for patients with breast cancer, while the expression of Pygo2 exerted a positive correlation to poor prognosis." (PMID 34299149, 2021). "Furthermore, loss of epithelial Pygo2 delayed mammary tumor onset in mouse mammary tumor virus (MMTV)-Wnt1 transgenic mice." (PMID 28055972, 2017). "Pygo2 plays a significant role in various malignancies, including prostate cancer, breast cancer, and esophageal cancer." (PMID 40771810, 2025). "PYGO2 ablation restored the chemotherapeutic drug sensitivity in breast-resistant cells and repressed breast cancer cell growth." (PMID 40034933, 2024). "FZD1 and Pygopus Family PHD Finger 2 (PYGO2), a recently discovered co-activator of Wnt/β-catenin -dependent transcription, were found overexpressed in chemotherapy-resistant breast cancer cell lines and to be essential for the maintenance of MDR1 expression." (PMID 35663403, 2022). "For instances, SNHG8 promotes the breast cancer cells proliferation by regulating the miR-335-5p/PYGO2 axis and accelerates ovarian cancer progression by miR-1270/ S100A11 axis." (PMID 35067159, 2022). "Inhibition of Pygo2 expression increased the sensitivity of breast cancer cells to chemotherapeutic drugs and suppressed tumor growth." (PMID 33854595, 2021). "MiR-516a-3p expression was expressed at a low level in human breast cancer tissues and cells, while the expression of Pygo2 was high." (PMID 34299149, 2021). "Abnormal expression of Pygo2 has been reported in several cancers such as breast cancer, glioma, esophageal squamous cell carcinoma, hepatocellular carcinoma and prostate cancer 7, 13, 14, 16, 33-35." (PMID 33854595, 2021). "IHC staining results showed that Pygo2 protein expression was up‐regulated in 68% (41/60) of the breast cancer tissue samples." (PMID 31273950, 2019). "In both luminal A and basal‐like of breast cancer, the expression of miR‐516a‐3p was lower and positive rate of Pygo2 expression was higher than that in adjacent normal breast tissues." (PMID 31273950, 2019). "IHC staining results showed that the level of Pygo2 protein in breast cancer tissues exhibiting high miR‐516a‐3p expression was lower than that in breast cancer tissues with low miR‐516a‐3p expression." (PMID 31273950, 2019). "To further explore the roles of miR‐516a‐3p and Pygo2 in breast cancer, we analysed the clinical significance of miR‐516a‐3p and Pygo2 expression in breast cancer patients." (PMID 31273950, 2019). "We confirmed that Pygo2 expression was attenuated in breast cancer tissues with high miR‐516a‐3p level compared with breast cancer tissues exhibiting low miR‐516a‐3p level through IHC staining analysis." (PMID 31273950, 2019). "In the present study, we found that miR‐516a‐3p expression was down‐regulated and Pygopus2 (Pygo2) expression was up‐regulated in human breast cancer tissues and cells." (PMID 31273950, 2019). "In this study, we found that miR‐516a‐3p expression was decreased and that of Pygo2 was up‐regulated in human breast cancer tissue and cells lines." (PMID 31273950, 2019). "In summary, we confirmed that the expression of miR‐516a‐3p was decreased and that of Pygo2 was increased in human breast cancer." (PMID 31273950, 2019). "We found that Pygo2 was a target of miR‐516a‐3p, and miR‐516a‐3p suppressed breast cancer cell growth and metastasis by inhibiting the Pygo2/Wnt/β‐catenin pathway, which were never reported." (PMID 31273950, 2019). "Through analysing the clinicopathological characteristics, we demonstrated that low miR‐516a‐3p expression or positive Pygo2 expression was a predictor of poor prognosis for patients with breast cancer." (PMID 31273950, 2019). "The reduction of miR‐516a‐3p expression and the overexpression of Pygo2 were related to poor clinical features and a worse prognosis in breast cancer patients." (PMID 31273950, 2019).
breast carcinoma (continued). "To assess the expression level of miR‐516a‐3p and Pygo2 in breast cancer, we detected their expression in 60 paired breast cancer tissue and matched normal breast tissue samples." (PMID 31273950, 2019). "IHC staining results showed that E‐cadherin protein was up‐regulated and Pygo2 protein and vimentin protein were down‐regulated in breast cancer tumour tissues treated with miR‐516a‐3p angomir." (PMID 31273950, 2019). "Pygo2 has been reported to be over-expressed in several malignant tumors, including those of epithelial ovarian cancer, breast cancer and human glioma, and appears to play an important role in the growth of these tumors." (PMID 28427190, 2017). "A new nuclear component of the Wnt signaling pathway, Pygo2, was upregulated in several tumors and is required for growth of epithelial ovarian cancer and breast cancer." (PMID 25797263, 2015). "In addition to prostate and breast cancer, Pygo2 also significantly promotes the occurrence and development of other malignancies, including esophageal cancer, colon cancer, and liver cancer." (PMID 40771810, 2025). "One other point worth emphasizing is our previous study also demonstrated Pygo2 could modulate MDR1 activation in breast cancer by directly binding to β-catenin, thus regulating the Wnt/β-catenin signaling pathway." (PMID 33854595, 2021). "Furthermore, we showed that miR‐516a‐3p suppressed cell proliferation, metastasis and EMT of breast cancer cells by inhibiting Pygo2 expression." (PMID 31273950, 2019). "In fact, PYGO2 was the most upregulated gene in chemo-resistant breast cancer cells." (PMID 31921125, 2019). "A detailed analysis of expression levels of each PHF in the five breast cancer subtypes also revealed that expression levels of PYGO2 and KDM5B were higher in Luminal, HER2+, and basal-like, compared with their expression levels in the normal-like subtype of breast cancer." (PMID 28055972, 2017). "What's more, abnormal Pygo2 expression has been reported in breast cancer, lung cancer, and glioma." (PMID 25871475, 2015). "Notably, PYGO2 has been proven to be up-regulated in breast cancer." (PMID 34362407, 2021). "For example, Pygo2 was found to possess the ability to directly bind to histone H3 trimethylated at lysine 4 (H3K4me3), associate with histone-modifying enzymes and recruits them to recruit chromatin to facilitate H3K4 trimethylation and histone acetylation in breast cancer cells." (PMID 28427190, 2017). "For instance, in breast cancer, SNHG8 accelerates cell migration and proliferation by miR-335-5p and PYGO2." (PMID 35067159, 2022). "As expected, PYGO2 inhibition restored drug sensitivity in MDR cells by decreasing ABCB1 expression, reducing the breast cancer stem cell subset following chemotherapy." (PMID 31921125, 2019). "Our results showed that a low expression of miR‐516a‐3p or positive expression of Pygo2 was related to lymph node metastasis, increased tumour size, higher TNM stage and worse prognostic in breast cancer patients." (PMID 31273950, 2019). "Taken together, these results show that miR‐516a‐3p inhibits breast cancer cell growth, metastasis and EMT by blocking the Pygo2/ Wnt/β‐catenin pathway." (PMID 31273950, 2019). "Furthermore, RNA samples from tumors extracted by surgery from 64 paired patients significantly increased PYGO2 and/or ABCB1 expression after chemotherapy, thus underlining a crucial role for the WNT/β-catenin pathway mediated by PYGO2 in the clinical chemoresistance of breast cancer." (PMID 31921125, 2019). "We demonstrated that miR‐516a‐3p inhibited breast cancer cell growth, metastasis and EMT by blocking the Pygo2/Wnt/β‐catenin signalling pathway both in vitro and in vivo." (PMID 31273950, 2019). "Again, mRNA expression levels of PYGO2 and KDM5B were higher in Luminal, HER2+, and basal-like breast cancers, and ZMYND8 was higher in Luminal B and HER2+ subtypes compared with that in the normal-like subtype in the METABRIC dataset (p < 0.001)." (PMID 28055972, 2017).
breast carcinoma (continued). "We found that three PHFs (PYGO2, KDM5B, and PHF20L1) were overexpressed at the mRNA level (Z-score > 1) in more than 40% of breast cancers." (PMID 28055972, 2017). "In this study, we identified four PHFs, PYGO2, KDM5B, PHF20L1, and ASH1L, which were most commonly amplified/overexpressed in breast cancer." (PMID 28055972, 2017). "Furthermore, in human breast cancer-derived MBA-MB231 cells, PYGO2 interacted with H3K4me2/3 to regulate mammosphere formation." (PMID 37233752, 2023). "Moreover, the miR-619-5p target gene Pygo2 was reported in previous studies to activate MDR1 expression and mediate chemoresistance in human glioma cancer and breast cancer via the Wnt/β-catenin pathway." (PMID 32727463, 2020). "Either miR‐516a‐3p expression or Pygo2 expression was not related to molecular subtypes of breast cancer, but they were therapeutic targets and potential prognostic biomarkers of breast cancer." (PMID 31273950, 2019). "Finally, xenograft tumour models were used to show that miR‐516a‐3p inhibited breast cancer cell growth and EMT via suppressing the Pygo2/Wnt signalling pathway." (PMID 31273950, 2019). "We found that increasing Pygo2 expression could reverse the effect of miR‐516a‐3p on the proliferation, migration, invasion and EMT of breast cancer cells." (PMID 31273950, 2019). "Pygopus2 (Pygo2), a newly identified components of the Wnt/β-catenin signaling pathway, was reported to activate MDR1 expression and mediate chemoresistance in human brain glioma and breast cancer via the Wnt/β-catenin signaling pathway by our team and other researchers." (PMID 32727463, 2020). "In addition, Pygo2 can facilitates histone methyltransferase (HMT) and histone acetyltransferase (HAT) interaction with β-catenin and further augment Wnt1-induced, TCF/LEF-dependent transcriptional activation in breast cancer cells." (PMID 25871475, 2015).
colorectal cancer (10 papers, 2008 to 2024). A primary or metastatic malignant neoplasm that affects the colon or rectum. "This interplay between Sam68 and Pygo2 is susceptible to control the pro-proliferation versus pro-differentiation/apoptosis activation balance of the canonical Wnt pathway according to the “just-right model” in colorectal cancer." (PMID 37792222, 2024). "Suppression of PYGO2 mRNA can inhibit the expression of Wnt/β-catenin signaling target genes in colorectal cancer." (PMID 40034933, 2024). "For example, PYGO1 is involved in colorectal cancer, while PYGO2 was shown to be a tumor promoter in mice." (PMID 31568528, 2019). "We also found ChiLS components associated with Pygo2 in stably transfected HEK293T cell lines, and with recombinant triple-NPF baits in lysates from mouse brains and colorectal cancer cell lines." (PMID 26312500, 2015). "Recently, Sam68 nuclear accumulation was suggested as a repressor of Pygo2-dependent canonical Wnt activation in colorectal cancer, where enhanced formation of CBP-Sam68 complexes would favor Pygo2 acetylation by p300 and subsequent nuclear export." (PMID 37792222, 2024). "Moreover, in the immortalized monkey kidney-derived COS cell line and the human colorectal cancer-derived SW480 cell line, PYGO2 promotes the nuclear translocation of β-catenin into the nucleus." (PMID 37233752, 2023).
glioma (9 papers, 2015 to 2024). A benign or malignant brain and spinal cord tumor that arises from glial cells (astrocytes, oligodendrocytes, ependymal cells). "In glioma cancer cells, in addition to overexpression of PYGO2 in the tumor cells, an association between the PYGO2 overexpression and the tumor grade was also reported." (PMID 40034933, 2024). "To assess a potential of Pygo2 as diagnostic and prognostic marker of glioma, we generated ROC curves and found that the Pygo2 mRNA level in glioma tissues substantially differs from that in control subjects, with an AUC value of 0.91." (PMID 26902498, 2016). "In conclusion, these results demonstrated that the molecular mechanism by which Pygo2 inhibits the efficacy of PTX-induced apoptosis in human glioma U-87MG and U251 cells involves two relevant activities." (PMID 28427190, 2017). "In this work, we aimed to determine the role of Pygo2 in the drug resistance of human glioma cells after treatment with PTX." (PMID 28427190, 2017). "Overall, our results indicate that Pygo2 enhances the proliferation of glioma cell lines treated with PTX and promotes PTX multidrug resistance in human brain glioma U-87MG and U251 cells." (PMID 28427190, 2017). "Cell migration and invasion were further evaluated in glioma U-87MG cells treated with PTX by examining the effects of exogenous Pygo2." (PMID 28427190, 2017). "MTT and trypan blue dye exclusion assays were performed to examine the effects of exogenous Pygo2 on the proliferation and viability, respectively, of the human glioma cell line U-87MG." (PMID 28427190, 2017). "Taken together, our results demonstrated that high Pygo2 levels enhance the invasion and migration capacity of human glioma U-87MG cells treated with PTX." (PMID 28427190, 2017). "The relative Pygo2 mRNA expression was detected by qRT-PCR in human glioma U-87MG and U251 cell lines after treatment with 30 nM PTX for 48 h." (PMID 28427190, 2017). "Pygo2 mRNA expression in the majority (152 out of 209) of primary glioma tissue samples (d) was increased compared with that in normal tissues (n = 9) (a), while peritumoral tissues (n = 13) (b) showed no significant changes." (PMID 26902498, 2016). "We also confirmed that Pygo2 was located in the nucleus of glioma cells using immunofluorescence staining and immunohistochemistry." (PMID 26902498, 2016). "Western blot analysis was then used to examine the protein expression of Pygo2 in glioma tissues which were classified into anaplastic astrocytoma tissue, diffuse astrocytoma tissue, yellow astrocytoma tissue, and normal tissue." (PMID 26902498, 2016). "For this we performed MTT assays and found that the proliferation of glioma U251 and U-87MG cells is significantly decreased by Pygo2 knockdown." (PMID 26902498, 2016). "To investigate roles of Pygo2 protein in the β-catenin pathway in glioma, we performed TOP/FOP flash analysis using the TOPflash reporter system in human brain glioma U-87MG and U251 cell lines." (PMID 26902498, 2016). "Here, we investigated the Pygo2 expression profile in human brain glioma and found that the Pygo2 protein and mRNA were over expressed in the majority of patient glioma tumor tissues." (PMID 26902498, 2016). "Using the criterion value of 1.4, the sensitivity and specificity values were 0.78 and 1, respectively, to identify a patient with glioma, indicating that Pygo2 serves as an excellent glioma marker." (PMID 26902498, 2016). "Taken together, our data demonstrated that Pygo2 knockdown significantly inhibits glioma cell proliferation, invasion and migration." (PMID 26902498, 2016). "We next examined the effects of Pygo2 on malignant phenotypes in glioma cells, including proliferation, migration and invasion." (PMID 26902498, 2016). "Here we demonstrated that the mRNA and protein of Pygo2 are both elevated in human glioma tissues and cell lines compared to normal tissues and paraneoplastic tissues." (PMID 26902498, 2016).
glioma (continued). "It has been shown that inhibiting PYGO2 protein expression prevents cell proliferation in glioma." (PMID 40034933, 2024). "Moreover, our previous study found that Pygo2 mRNA and protein expression were significantly higher in glioma tissues and cells, and abnormally high expression of Pygo2 protein in glioma patients was correlated with a poor prognosis." (PMID 28427190, 2017). "Another study reported that inhibiting the expression of Pygo2 could decrease the proliferation, colony formation, and BrdU incorporation of gliomas by reducing cyclin D1, a downstream gene of the Wnt/β-catenin signaling pathway." (PMID 28837560, 2017). "Furthermore, a multivariate analysis was performed and found that high Pygo2 expression is an independent feature for poor overall survival in human glioma patients (HR = 5.798, 95% CI = 1.137–29.582, P = 0.035)." (PMID 26902498, 2016). "Furthermore, we showed that Pygo2 expression strongly correlates with clinical and pathological features of glioma." (PMID 26902498, 2016). "We also used western blot and qRT-PCR analyses to examine the expression of Pygo2 and β-actin (as control) in five glioma cell lines, TJ861, A172, U373, U251 and U-87MG and found that Pygo2 protein and mRNA levels are both up-regulated as compared with normal human microglia primary cells (Glia)." (PMID 26902498, 2016). "In the present study, we discovered that Pygo2 mRNA and protein levels were up-regulated in the majority of (152/209) human brain glioma tissues and five glioma cell lines, and significantly correlated with the age, the WHO tumor classification and poor patient survival." (PMID 26902498, 2016). "In addition, knockdown of Pygo2 inhibits glioma cell proliferation, migration and invasion." (PMID 28427190, 2017). "In fact, the expression of Pygo2 was significantly higher in ttissues from the elderly and more severe (classified by WHO) glioma patients." (PMID 26902498, 2016). "Overall, glioma from astrocytoma and glioblastoma Multiforme, but not normal or peritumoral tissues, had weak (“+”, 7.38%) to strong (“+++”, 29.53%) Pygo2 nuclear accumulation." (PMID 26902498, 2016). "Further, we demonstrated that the involvement of Pygo2 in the activation of the Wnt pathway in human glioma progression is through up-regulation of the H3K4me3 (but not H3K4me2) by promoting the recruitment of the histone methyltransferase MLL1/MLL2 complex to Wnt target gene promoters." (PMID 26902498, 2016).